CTLA4 (cytotoxic T-lymphocyte associated protein 4)
Diseases named in the same sentence as CTLA4 in open-access papers (continued):
Sharing a sentence is not in itself a finding about the gene and the disease.
tumor (continued). "However the immune milieu of the tumor microenvironment could be modulated through complex mechanisms which facilitate responsiveness to CTLA-4 inhibition." (PMID 28807052, 2017). "Although pharmacodynamics of these immune modulators are complex, recent studies strongly support the notion that altered peptide ligands presented on tumor cells representing neoantigens may play an essential role in tumor rejection by T cells activated by anti-CTLA4 and anti-PD-1 antibodies." (PMID 29250075, 2017). "Since trAbs not only mediate direct tumor cell killing, but also elicit a vaccination effect, we then asked whether the immunologic memory induced by trAbs is affected by the combination with anti-CTLA-4 treatment." (PMID 27966460, 2017). "Also, because these drugs are affecting MHC-1 on the tumor cells, it may be worth exploring their use with an anti-PD-1, anti-PD-L1, or anti-CTLA-4 checkpoint inhibitors, which enhance the activity of effector T cells." (PMID 28881567, 2017). "Any of these mutations would prevent signaling in response to IFN-γ and give an advantage to the tumor cells escaping from T cells, thereby resulting in primary resistance to anti-CTLA-4 therapy, and may also be a reason for the resistance to PD-1/PD-L1 blockade therapy." (PMID 29299180, 2017). "Moreover, CTLA-4 inhibitors frequently induce an increase in T cells within the tumor." (PMID 29262592, 2017). "Thus, one can speculate that anti-CTLA-4 therapy may also, at least indirectly, improve NK cell contribution to anti-tumor immune response." (PMID 29023417, 2017). "However, while large numbers of CD8+ T cells can be found in some types of tumors, tumor progression often still persists; in these cases inhibitory mechanisms such as the immunosuppressive CD8+ T cell receptors, PD-1, and CTLA-4 as well as tumor-expressed PD-L1 are often involved." (PMID 29072624, 2017). "Importantly, CTLA-4 engagement improves the suppressive activity of Tregs which are typically concentrated in tumor tissues where they contribute to the inhibition of anti-tumor effector responses." (PMID 28404974, 2017). "Similarly, we found a significant increase in CD8 T cells and CD8/Treg ratio as well as moderate inhibition of Treg, not only in the irradiated tumor but also in the unirradiated tumor when anti-PD-L1 and anti-CTLA-4 antibodies were combined with X-ray irradiation." (PMID 29253865, 2017). "Targeting the immune checkpoints CTLA-4 and PD-1 with monoclonal antibodies (MAbs) aim to release natural breaks that control immune function in physiological situations, to increase and sustain antitumor immune responses, either to shared tumor Ags (i.e., cancer testis Ags) and/or to neoantigens." (PMID 28620382, 2017). "Therefore, therapy with 7 and γδ T cells could be further combined with checkpoint blockade with anti-PD-1/anti-PD-L1 and/or anti-CTLA-4 antibodies to activate anti-tumor CD4 and CD8 αβ T cells that are already present." (PMID 28729550, 2017). "Interestingly, we observed that CTLA-4 but not PD-L1 based immunotherapy selectively enhanced the anti-tumor phenotype of Cblb-deficient mice." (PMID 28611299, 2017). "However, it should be taken into account that the effects of AZA in the expression of immunomodulatory signatures are diverse and additional aspects might be involved in boosting the anti-tumor immune responses mediated by anti-PD-L1 and anti-CTLA4 treatments." (PMID 28545238, 2017). "Therefore, ongoing studies are now aimed at further deciphering the pathway involved, as well as to investigate a putative role for lumican in fostering tumor response to immunotherapeutic approaches such as immune checkpoint inhibitors anti-PD-1 and anti-CTLA-4." (PMID 28794454, 2017). "Therefore, effects of anti-CTLA-4 antibodies in tumor therapy could also be partially mediated due to their effects on the glycolytic metabolism." (PMID 28447025, 2017).
tumor (continued). "Cytotoxic T-lymphocyte-associated protein 4 (CTLA-4) and programmed cell death protein 1 (PD-1) are two inhibitory receptors expressed by T cells that have become therapeutic targets to mitigate the immunosuppressive tumor environment and promote antitumor immunity." (PMID 28536351, 2017). "Selumetinib monotherapy, and combination with anti-CTLA-4, led to significant decreases in tumor-infiltrating gMDSC/neutrophil when compared to control or anti-CTLA-4 alone; suggesting that MEK inhibition may improve the tumor microenvironment by reducing immunosuppressive cell types." (PMID 28807001, 2017). "As the role of CTLA-4 functioning as a brake in T cell responses became better understood, Allison recognized that taking the brake off from T cells might help unleash anti-tumor effector responses." (PMID 28497159, 2017). "In addition, CTLA-4 expression on tumor specific Tregs could contribute to tumor immune escape by increasing the suppressive anti-tumor immunity and by downregulating CD80/CD86 on antigen presenting cells." (PMID 28073373, 2017). "Moreover, monoclonal antibodies targeting CTLA-4 enhance T cell mediated anti-tumor immunity." (PMID 28707078, 2017). "However, CTLA-4 signaling also enhances immunosuppression in other ways, e.g., by promoting the activity of regulatory T cells (Tregs) inside the tumor-microenvironment, and the relative importance of these different mechanisms is not fully understood nor their contribution to therapy success." (PMID 27847783, 2016). "In addition to T-cells, CTLA-4 expression is known to be present in a variety of cell types, including tumor cells, but the functional pathway is still unknown." (PMID 27741514, 2016). "Furthermore, when these poxvirus-based immunotherapy candidates were used in combination with CTLA-4 blockade, increased lymphocyte proliferation, IFNγ production, and T cell avidity resulted in tumor rejection through immune responses to self-antigens in tolerant mouse models." (PMID 26961085, 2016). "One can hypothesize that radiation therapy can transform the tumor into an in situ individualized vaccine, recruiting immune cells to the tumor microenvironment, and the combination of radiation with blocking antibodies against PD-L1 or CTLA-4 can further induce an anti-tumor effect." (PMID 27854240, 2016). "PLGA-ICG-R837-based photothermal treatment combined with anti-CTLA4 therapy could protect treated mice against tumour cells rechallenging 40 days post ablation of primary tumours, demonstrating the strong immune-memory effect to protect mice from cancer relapse." (PMID 27767031, 2016). "In the case of immunotherapy, considerations beyond the tumor may also be particularly important; for example, early laboratory studies have shown that the composition of the intestinal microbiota significantly impacts the efficacy of CTLA-4/PD-1 inhibitors." (PMID 29034103, 2016). "However, CTLA-4 protein expression can be stimulated in TIMCs and tumor cells." (PMID 27050369, 2016). "Overall, the cytokine profiles indicate that the functional quality of the tumor antigen-specific T cell response, in addition to the magnitude of the tumor-specific T cell response, is augmented even further by the combination of active immunotherapy plus CTLA-4 checkpoint blockade." (PMID 26961085, 2016). "Hence, a combination of ECT with anti-CTLA4 or anti-PD1 antibodies could be an elegant way to destroy the initial nodule while raising efficient anti-tumor responses to ultimately eliminate remaining and circulating cancer cells." (PMID 26993326, 2016). "One route of escape from immune cell destruction is by expressing inhibitory molecules, such as CTLA-4 and PD-L1, on their cell surface, which bind to the respective receptors on the surface of immune cells, prompting an inhibitory immune response, resulting in tumor cell growth." (PMID 27854240, 2016).
tumor (continued). "Therefore, it is obviously that immunological responses triggered after PLGA-ICG-R837-based photothermal ablation of primary tumours in combination with anti-CTLA-4 therapy can effectively inhibit cancer metastasis and prolong the survival of mice with spreading tumour cells." (PMID 27767031, 2016). "Similarly, in mouse models of colon carcinoma (CT26 cell line) and ovarian carcinoma (ID8-VEGF cell line), dual block (both anti-PD1 and anti-CTLA-4) combined with tumor vaccine leads to effective tumor rejection through the restoration of effector T cell function." (PMID 27917371, 2016). "At present, although no single immunological or tumor-related factor has been found to solely determine the response to an immunotherapeutic agent, the expression of CTLA-4 in the tumor or TILs may represent a target, and CTLA-4 blockade may provide therapeutic benefits for NPC." (PMID 26918337, 2016). "Thus, CTLA-4 may function in the periphery as a negative regulator of effector T cell-mediated anti-tumor immunity, thereby allowing unrestrained tumor progression due to impaired host immune surveillance." (PMID 27050369, 2016). "CTLA-4 is also involved in tumor immunity associated with negative regulation of T-cell receptors." (PMID 27741514, 2016). "One of the repurposed drugs that we identified in this manner, meticrane, has not been associated with any anti-tumour or pro-immune effect and could not have been predicted to work in synergy with anti-CTLA4 otherwise." (PMID 26193793, 2015). "Although other mechanisms may contribute to the therapeutic responses, our data suggests that CTLA-4 blockade may help recruit NK cells to the tumor microenvironment while IL-2 (alone and in combination with CTLA-4 blockade) altered the maturation of tumor-infiltrating NK cells." (PMID 25992289, 2015). "As several checkpoint inhibitors (for example, antibodies blocking CTLA-4 or PD-1) are currently undergoing testing as a means to restore anti-tumor immune responses in human trials, it is conceivable that the clinical potential of such combination strategies could be exploited in the near future." (PMID 26295610, 2015). "The blockade of these pathways by the anti-CTLA4, anti-PD-1 and anti-PD-L1 antibodies may prevent this downregulation and allows T-cells to maintain their antitumor property and ability to mediate the tumor cell death." (PMID 26086854, 2015). "In addition, Tregs may exert their immunosuppressive effects by both directly interacting with tumor cells via the expression of surface molecules such as CTLA-4, and via the secretion of cytokines such as IL-10 and TGF-β43." (PMID 26394925, 2015). "Remarkable clinical activity with rapid and deep tumor reduction has been reported in 65 % of 53 patients with advanced melanoma treated with a combination of nivolumab, which is different from the published data on monotherapy PD-1 inhibitor, and ipilimumab, CTLA4 inhibitor." (PMID 26674411, 2015). "The success of CTLA-4 inhibition and PD-1/PD-L1 inhibition in the treatment of cancer has lead to greater appreciation of the complexity of tumor microenvironment and the various interacting components that may present as unique opportunities for manipulation to control cancer." (PMID 27508107, 2015). "It is possible that anti-tumor synergy produced by anti-PD-L1 in combination with anti-LAG-3 or anti-TIM-3 antibodies may be a less toxic alternative to anti-PD-L1 in combination with anti-CTLA4 antibodies." (PMID 25614821, 2015). "Interestingly, the combination of BMS-908662 with a CTLA-4 blockade improved anti-tumor action." (PMID 25709607, 2015). "Human CTLA-4 also induced anti-CTLA-4 antibody and may promote anti-tumor immune responses." (PMID 25265018, 2014).
tumor (continued). "Moreover, anti-CTLA-4 antibody treatment after surgical resection of the primary tumour facilitated the elimination of lymph node metastases, suggesting that this immunotherapy has potential to be used as an adjunct therapy to eliminate residual metastatic PCa after surgery." (PMID 25276838, 2014). "Therefore, 64Cu-DOTA-anti-CTLA-4 mAb is useful for evaluating CTLA-4 expression in the tumor." (PMID 25365349, 2014). "In addition, recent research showed that various tumor cells also express CTLA-4." (PMID 25365349, 2014). "Two fully human mAbs that bind CTLA-4, tremelimumab (CP-675,206, Pfizer, New York, NY) and ipilimumab (YervoyTM, Bristol-Myers Squibb, Princeton, NJ), have been in clinical development over the past decade, and both agents have shown activity in inducing tumor regression in clinical studies." (PMID 23873089, 2013). "Thus, when given anti-CTLA-4 blocking antibodies the negative regulation mediated by CTLA4 is blocked, TGFβ and IL-10 remain in the postradiation tumor environment, and it is likely that these factors will continue to limit adaptive immune function despite CTLA4 blockade." (PMID 23653658, 2013). "CTLA-4 is a negative regulator of T-cell proliferation and activation, recent studies shows that it plays an important role in cancer immunosurveillance and may be involved in tumor development and progression." (PMID 24376736, 2013). "While additional studies might be helpful in elucidating the underlying mechanism, it is clear from our data that administration of GVAX prior to anti-CTLA-4 was superior in stimulating anti-tumor CD8 T cell activity as compared with upfront administration of anti-CTLA-4 or either therapy alone." (PMID 23557194, 2013). "Furthermore, our observation that the suppressive function of IL-35-expressing CD8+CTLA-4+ Treg is temporally regulated following antigen-specific immunization suggests that this population may be able to be modulated depending on the tumor microenvironment." (PMID 24151492, 2013). "Limiting antitumor T-cell responses via exploitation of checkpoint pathways (such as those involving CTLA-4 or PD-1) serves to prevent significant tumor destruction and leads to an equilibrium between the tumor and immune system that typically progresses to tumor escape." (PMID 24403232, 2013). "Importantly, a combination of anti-CD137/PD-1/CTLA4 mAbs was shown to be therapeutically efficacious (and sometimes curative) in all of 4 mouse models investigated when delivered to the tumor microenvironment, and the efficacy was further increased by also including a mAb to CD19." (PMID 24367702, 2013). "Moreover, flow cytometry revealed that PD-1 and CTLA-4 were mostly co-expressed in tumor cells harvested from the D61540 CX, suggesting that expression of these two T cell-associated inhibitory signaling molecules in CRC cells may be coordinately regulated." (PMID 24278200, 2013). "In tumor, CTLA-4 is upregulated on the T cells with the help of TGF-β (a suppressive cytokine secreted by the tumor cells),and during the early stage of tumorigenesis, CTLA-4 may elevate the T-cell activation threshold, thereby attenuating the antitumor response and increasing cancer susceptibility." (PMID 24376736, 2013). "Thus, the presence of a more tolerogenic CTLA-4 genotype, for instance related to a more frequent production of sCTLA-4, could represent a potential form of tumor immune evasion." (PMID 23049754, 2012). "Similarly, the blockade of CTLA-4 or PD-1 may enhance vaccine-elicited immune responses and anti-tumor activity." (PMID 22485134, 2012). "Effective vaccines must overcome escape mechanisms exploited by tumor cells (e.g., antigen loss, expression of immunosuppressive cytokines, induction of Tregs and MDSC) as well as the tumor's capacity to affect T cell trafficking and normal immune regulation (e.g., via CTLA-4 and PD-1)." (PMID 21281484, 2011).
tumor (continued). "This pattern of delayed response is peculiar of anti-CTLA4 antibodies and is the reason why novel immune-related response criteria were developed, according to which progressive disease is defined as an increase ≥25% in the sum of tumor diameters confirmed by two scans at least 4 weeks apart." (PMID 22190975, 2011). "In addition to the established, albeit toxic and rather ineffective treatments of interferon alpha in the adjuvant setting and Interleukin 2 in the advanced setting, new therapies with anti-CTLA-4 antibodies or specific (individualized) tumor vaccines are being developed." (PMID 20224761, 2010). "Tumor-infiltrating CD8+ T-cells also expressed significantly lower levels of exhaustion markers, including LAG-3, CTLA4 and TIM3." (PMID 41431358, 2026). "We introduce CleTAC and validate its efficacy through cellular and animal tumour model studies, demonstrating that engineered CAR-T cells with reduced membrane CTLA4 exhibit improved anti-tumour performance." (PMID 41328344, 2026). "Immune checkpoint proteins including PD-1, CTLA-4, LAG-3, TIM-3, and TIGIT regulate T-cell functions, which are essential for anti-tumor immunity." (PMID 41681956, 2026). "Genetic silencing of AADAT in orthotopic murine TNBC models curtailed primary tumor growth and distant metastasis in a CD8+ T-cell-dependent manner, enhanced effector T-cell activation, and sensitized tumors to dual PD-1/CTLA-4 blockade." (PMID 41659489, 2026). "Although PKM-ASO monotherapy had a limited effect in an immunodeficient mouse model of PDAC, synergy between PKM-ASO and anti-CTLA-4 immune checkpoint blockade (ICB), which targets Tregs, restricted tumor growth in an immunocompetent mouse model." (PMID 42009652, 2026). "One tumor in each mouse was treated with partial Cryo, systemic dual CPI (anti-PD-1 and anti-CTLA-4), intratumoral TLR9 agonist CpG, or combinations thereof, while the second tumor was untreated." (PMID 41677856, 2026). "4T1-tumor-bearing BALB/c mice were used to evaluate the therapy response to four treatments: saline control, SAHA, anti-PD-1 + anti-CTLA-4 checkpoint blockade IMT, or a combination of SAHA + IMT." (PMID 42198232, 2026). "Using the CT1BA5 tumor model, we show that ecDNA tumors are immunologically “cold”, exhibiting poor lymphocyte infiltration and being refractory to anti-PDL1 or anti-CTLA4 immune checkpoint blockade therapies." (PMID 41509453, 2026). "We present a comprehensive transcriptomics analysis of metastatic and primary tumor biopsies from MSS mCRC patients treated with botensilimab (BOT; Fc-enhanced anti-CTLA-4) ± balstilimab (BAL; anti-PD-1)." (PMID 42298180, 2026). "Another study used DSP to characterize the tumor and adjacent stroma and identified differentially expressed immune markers (OXL40L, CTLA4, CD11c), which conveyed prognostic information." (PMID 41545625, 2026). "We found that CTLA4 expression was strongly positively correlated with the immune score and CD8+ T-cell infiltration, and the tumor cells barely express CTLA4." (PMID 41596281, 2026). "Meanwhile, the level of immunosuppression factors in tumor tissues, such as LAG-3, CTLA-4, and IDO-1, increased significantly." (PMID 40487392, 2025). "Our results identify an intricate interplay between the Fc effector function of anti-CTLA-4 antibodies, IFNγ-producing effector CD4+ T cells, and tumor endothelial cells." (PMID 40460830, 2025). "Tumour-bearing mice were i.p. injected with different combinations of anti-PD-1, anti-TIGIT, and anti-CTLA-4 antibodies at a dose of 0.2 mg/mouse, respectively." (PMID 39939955, 2025). "Immune checkpoints—such as PD-1, CTLA-4, LAG3, and TIM3—also play central roles in mediating T-cell exhaustion and promoting immune evasion by interacting with ligands expressed on tumor and stromal cells." (PMID 41012682, 2025).